PRRX1 (paired related homeobox 1)
Diseases named in the same sentence as PRRX1 in open-access papers (continued):
Sharing a sentence is not in itself a finding about the gene and the disease.
cancer (continued). "The PRRX1‐positive staining was mainly located in nucleuses of cancer cells." (PMID 31657086, 2020). "PRRX1 is an established regulator of EMT in cancer cells, supporting that PRRX1 may regulate COL6A3 during EMT." (PMID 33214660, 2020). "Unlike other EMT-associated TFs, the loss of Prrx1 is required for cancer cells to metastasize in vivo in carcinomas." (PMID 33348918, 2020). "The PRRX1‐induced EMT of cancer cells helps to educate newly recruited FFAs by targeting PPARG2." (PMID 31657086, 2020). "However, the molecular mechanism of PRRX1 in cancer malignancy remains to be elucidated." (PMID 38448751, 2024). "Thus, fibroblast-specific Prrx1 depletion induces long-term sustained CR in established cancers." (PMID 35589735, 2022). "In pan-cancer analysis, SHOX2 expression positive correlated with CDKN2C (R = 0.41), COL6A1 (R = 0.35), COL6A2 (R = 0.37), DCHS1 (R = 0.37), MAPK7 (R = 0.34), PRRX1 (R = 0.37), RAB23 (R = 0.36) and RSRC1 (R = 0.36) via GEPIA2." (PMID 37170390, 2023). "Prrx1 in fibroblasts was deleted by injecting single-guide RNA (sgRNA) against Prrx1 into the FSP1;creCAS9EGFP mice, and LLC1-Luc-GFP cancer cells were subcutaneously transplanted." (PMID 35589735, 2022). "First, to gain a broad insight into the Prrx1 role in CAF in overall human tumors, the scRNA-seq data of seven cancer types were analyzed." (PMID 35589735, 2022). "Unsupervised principal component analysis with the main cancer invasiveness-enriched genes (ASPN, GLT8D2, OLFML2B, CRISPLD2, ADAM12, POSTN, and PRRX1) allowed for the discrimination of subgroups of BMAL1-dependent CRC patients (p = 9.9 × 10−4)." (PMID 34065633, 2021). "This loss of Prrx1 was associated with a reversion of EMT and induction of stem cell properties, suggesting that plasticity and EMT are not inextricably linked and the process of metastasis may require dynamic fluctuations between epithelial and mesenchymal states in cancer cells." (PMID 32391382, 2020). "Here, the authors uncover a gene regulatory network between Prrx1 and Snail1 that selects EMT mode in developing vertebrates and cancer cells." (PMID 31712603, 2019). "First, we examined coexpression of key component of the PFL; Twist1, Prrx1, and TNC in clinical samples such as patient tissue-derived ex vivo cultured CAFs, archived paraffin-embedded cancer tissues, and TCGA data." (PMID 30069061, 2018). "Based on online literature search, we found that OLR1, GPNMB, PRRX1 and BCAT1 promote cancer migration and invasion in various types of cancer." (PMID 29851214, 2018). "Ongoing stemness after MET has been suggested in studies examining PRRX1, a gene mediating EMT in migrating and invading cancer cells; downregulation of PRRX1 enables epithelial reversion, maintenance of stemness, and metastasis formation." (PMID 28750639, 2017). "Of note, the motif essential for PRRX1 oligomerization is unique to PRRX1 and not found in other HD proteins, making it a potential target for improving cancer treatment." (PMID 40114375, 2025). "The non-canonical EMT transcription factor paired-related homeobox 1 (PRRX1) overexpression activates EMT in specific cancers, comprising those of the stomach, colorectum, pancreas, or breast, and fosters a migratory and invasive phenotype." (PMID 38397421, 2024). "CC-3 represented the mesenchymal-like cancer cell subpopulation that expressed mesenchymal genes such as Prrx1, Col6a1, Thy1, and Vim, but not epithelial marker genes such as Epcam and Cdh1." (PMID 37190324, 2023). "Using copy number analysis (anueploidity) of the scRNA-seq and cell-type annotation, we confirmed that most PRRX1-expressing cells in the scRNA-seq data were not cancer cells." (PMID 35589735, 2022). "In conclusion, this study identified Prrx1 as an mTF of a lineage-dependent CAF subpopulation that shows myofibroblast-like phenotype and plays a critical role in promoting tumorigenesis, metastasis, and cancer recurrence." (PMID 35589735, 2022).
cancer (continued). "Taken together, our data suggest that PRRX1 may be a target in adipocytes and potentially other cell types to modulate COL6A3 expression in the context of pathological conditions including cancer." (PMID 33214660, 2020). "We believe that NANOGP8/TWIST/ZEB/PRRX1 may be the upstream regulators of EMT, and vimentin/N-caderin/E-caderin may be the structural components to endow cancer cells the EMT properties." (PMID 29689047, 2018). "Another phenomenon we observed is that, in NANOGP8 over-expressed cancer cells, expression of EMT signature genes such as TWIST1, PRRX1, ZEB, Vimentin, and N-caderin, was significantly up-regulates and expression of the epithelial marker E-caderin was reversely down-regulated." (PMID 29689047, 2018). "Yet other studies report the presence of proposed MET-type CSCs via downregulating PRRX1, rather than carcinoma cells that undergo an EMT." (PMID 30038266, 2018). "This hypothesis is supported by the recent report of a genetic interaction between PRRX1 and TWIST1 to promote cellular invasion during embryogenesis and in cancer cells." (PMID 28769044, 2017). "To confirm that regulation of immunomodulation and metastasis by master regulators AIF1 and PRRX1 were not specific to the TCGA datasets, we independently validated gene interactions regulated by Set 1/Set 1-s and Set 2 for six cancers in in other datasets of six cancers." (PMID 26272668, 2015).
PRRX1 also shares sentences with these, for which no sentence is quoted: acute leukemia (2 papers); familial atrial fibrillation (2); idiopathic pulmonary fibrosis (2); infection (2); lymph node metastasis (2); oral squamous cell carcinoma (2); prostate carcinoma (2); thyroid carcinoma (2); uveal melanoma (2); acute myeloid leukemia (1); adrenocortical carcinoma (1); atopic dermatitis (1); benign tumours (1); breast invasive carcinoma (1); cardiovascular diseases (1); cholangiocarcinoma (1); chondroma (1); chronic myeloid leukemia (1); clear cell renal cell carcinoma (1); cleft palate (1); Cognitive impairment (1); diabetic nephropathy (1); digestive system tumours (1); dyslexia (1); Fibroadenoma (1); fibrosarcoma (1); head and neck carcinoma (1); hematological malignancies (1); hemorrhagic stroke (1); intracerebral hemorrhage (1).
A further 24 diseases each share a sentence with PRRX1 in 1 paper.